KLRD1 (killer cell lectin like receptor D1)
Diseases named in the same sentence as KLRD1 in open-access papers (continued):
Sharing a sentence is not in itself a finding about the gene and the disease.
tumor (218 papers, 2009 to 2026). "High KLRD1 expression is linked to increased activity of immune microenvironment indicators, including cytotoxic T cells, inflammatory T cells, tumor-infiltrating lymphocytes, and tumor-associated lymphoid structures, further underscoring its potential in boosting immune responses." (PMID 39781341, 2025). "Supporting this, high KLRD1 expression correlates with increased activity of key immune components, including cytotoxic T cells, tumor-infiltrating lymphocytes, and inflammatory T cells, potentially enhancing the efficacy of immunotherapy." (PMID 39781341, 2025). "This further elucidates the multiple roles of KLRD1 in regulating immune responses within the tumor microenvironment." (PMID 39781341, 2025). "Immune infiltration analysis, conducted via CIBERSORT, assessed the relationship between KLRD1 expression and immune cell infiltration within the tumor microenvironment." (PMID 39781341, 2025). "Through the development of monoclonal antibodies targeting KLRD1, the binding between KLRD1 and its ligands can be blocked, thereby enhancing the anti-tumor activity of NK cells and T cells." (PMID 39781341, 2025). "This comprehensive analysis aims to elucidate how KLRD1 modulates critical aspects of tumor biology and evaluate its potential for advancing future cancer treatments." (PMID 39781341, 2025). "This study seeks to assess the potential of KLRD1 as a therapeutic target in tumor immunotherapy through an extensive pan-cancer analysis." (PMID 39781341, 2025). "This distribution suggests that KLRD1 plays varied roles depending on the tumor's immune context and molecular profile, influencing both tumor progression and its interaction with the immune system." (PMID 39781341, 2025). "Lastly, the loss of Arid2 promoted the expression of KLRD1 and inhibited TCF1 and TOX expression in the CXCR6+CD44+ cluster, further indicating an increased effector profile of tumor-specific CD8+ T cells following PBAF deletion." (PMID 37330910, 2023). "We also observed extensive interactions of KLRD1 and HLA family members between NK cells and other cell types, and interactions between tumor cells and other cell types related to extracellular matrix remodeling." (PMID 36028490, 2022). "Strikingly, CD8High T cells showed a high expression of granzyme B and KLRD1 in all investigated tumour entities." (PMID 36504430, 2022). "HLA-E and CD94 (KLRD1) was another one of the more significant immune cell-tumor interactions (on NK) during single-cell transcriptomic analysis of NPC." (PMID 33671917, 2021). "T cells (expressing Cd2, Cd3e, Cd3g, and Cd6) were the most abundant immune cell type in tumor tissues, followed by cytotoxic cells (expressing Gzma and Klrd1)." (PMID 32612611, 2020). "We also investigated NK inhibitory receptors: KLRC1 (NKG2A) and KLRD1 (CD94) that suppressed NK cell anti-tumor activity via binding HLA-E30 to evaluate differential NK cell-mediated effects in KIRP and SKCM." (PMID 32533054, 2020). "KLRD1 (CD94) is known to suppress NK activity against tumor cells via ligation with the NKG2A receptor on the tumor cell surface, followed by interaction with HLA-E receptor on the NK cell." (PMID 32552875, 2020). "To further explore the role of KLRD1 in the immune landscape of HNSC, we analyzed its association with immune checkpoints and subtypes, aiming to understand its link to key immune checkpoint regulation involved in immune evasion and tumor progression." (PMID 39781341, 2025). "Elevated expression of KLRD1 may play an important role in balancing tumor immune surveillance and immune evasion." (PMID 39781341, 2025). "It was speculated that KLRB1 and KLRD1 show reduced expression in the tumor microenvironment of patients with T-ALL/T-LBL, which can lead to immune response deficits." (PMID 38464517, 2024). "Notably, NK cells, which displayed high expression levels of GNLY, NKG7, CCL3, and KLRD1, were enriched in tumor tissues, especially in HM tissues." (PMID 37612267, 2023).
tumor (continued). "We also found one gene, KLRD1 (CD94), dysregulated in a direction that potentially sensitizes tumor cells to PD-1 blockade, which may be a mechanism that contributes to the success of PD-1 blockade in certain HCC patients." (PMID 31480259, 2019). "A starting point may be the HTICS Cell migration pathway genes (Nrp1, Npy, Cldn8) and their substitutes (Klrd1, Spink5, Itga8) identified herein—but other known markers of cancer cell dissemination or circulating tumor cells may be equally informative." (PMID 28632792, 2017). "The Nrp1 substitute, Klrd1 (Killer Cell Lectin-Like Receptor Subfamily D, Member 1), an antigen expressed on Natural Killer cells, may also be considered as target to block tumor dissemination." (PMID 28632792, 2017). "Tumor NK cells downregulated canonical NK activation markers, such as FASLG, TNFSF10, KLRK1, GZMB, and KLRD1, the latter having both inhibitory and activator capabilities but being a marker of favorable prognosis in human cancers if present in either the serum or tumor." (PMID 41208961, 2025). "Gene signatures associated with NK‐cell cytotoxicity and activation (Gzma, Prf1, Klrd1, Nkg7, and Klrk1) were markedly upregulated at high proportions of NK cells in nanoSTING@Mn combined with LLL on dLNs and Tumor, as compared to nanoSTING@Mn alone (bottom)." (PMID 41126739, 2026). "In contrary we found upregulated (EOMES, TNFSFR9, TIGIT, KLRD1) and downregulated genes (PAG1, GNLY, ANXA1, FGFBP2) that are involved in tumor escape from immune surveillance by suppressing T-cells or by reprogramming T-cells toward T-cell exhaustion." (PMID 40079005, 2025). "Tumor-infiltrating clusters NK1 and NK5 showed high expression of NK-activating receptors, including NKG2D-DAP10 (KLRK1/HCST), NKG2C (KLRC2), CD94 (KLRD1), and NKp30 (NCR3), suggesting that they were robustly activated." (PMID 40315330, 2025). "Many factors influence the expression of KLRD1 molecules, including cytokines such as IL-12 and IFN-gamma, viral infections, and tumor factors." (PMID 39781341, 2025). "Circulating tumor cells can enhance HLA-E expression and bind to CD94 (KLRD1)/NKG2A on NK cells, thereby weakening NK-mediated tumor cell killing and cDC1 recruitment via XCL2 secretion." (PMID 40959273, 2025). "Comparing T cell gene expression between treatments revealed a significant increase in Klrk1, Klrc2, Klrd1, Fasl, and Sema4a in CD4 T cells at the tumor site after HVJ-E/OX40 antibody injection." (PMID 39534532, 2024). "The main cell clusters included T cells (CD3E and CD3D), B cells (CD19), natural killer cells (NCAM1, FCGR3A and KLRD1), myeloid cells (CD86 and CD163) and tumor cells (EPCAM, KRT8 and KRT18)." (PMID 36497182, 2022). "CD8Low T cell showed enhanced ST2L and IL6ST (CD130) expression compared to CD8High T cells which expressed elevated KLRD1 (CD94) and granzyme B levels within the tumour microenvironment (TME)." (PMID 36504430, 2022). "NKG7, KLRD1, and KLRB1 are marker genes of T cells and NK cells, which is in line with the fact that the proportions of T and NK cells in tumor samples were significantly smaller than those in paracancerous tissues." (PMID 35967424, 2022). "Subsequently, we analyzed DEGs between tumor and normal tissues and selected the top five DEGs with the highest expression, which were SPP1, AKR1C2, AKR1B10, AGT, and EPHX1 in tumor tissues and NKG7, KLRD1, KLRB1, CCL5, and CST7 in normal tissues." (PMID 35967424, 2022). "NK cells bind to HSP70 through the killer cell lectin-like receptor D1 (KLRD1), resulting in granzyme B release and tumor cytolysis." (PMID 32218162, 2020). "Furthermore, the Tracking Tumor Immunophenotype (TIP) meta-server and Easier tool were employed to assess the role of KLRD1 in the cancer immunity cycle and to predict immunotherapy responses." (PMID 39781341, 2025).
tumor (continued). "The cell type-specific markers we used for cell annotation were as follows: T cell (CD3D); NK cell (KLRD1 and NKG7); plasma cell (IGKC and JCHAIN); Mast cell (KIT and TPSB2); tumour cell (CA9, NDUFA4L2 and SLC17A3); endothelium (PECAM1, PTPRB and KDR); mesangial cell (ACTA2 and PDGFRB)." (PMID 40830065, 2025). "Tumor-infiltrated NK cells expressed higher level of KLRC1(NKG2A) gene and KLRD1(CD94)." (PMID 34177887, 2021). "Cell surface receptors known to be bound with ex-HSP90 are (i) CD91/LRP1/A2MR expressed on tumor cells, immune cells, and EVs, (ii) toll-like receptors (TLRs), (iii) scavenger receptor expressed by endothelial cells-1 (SREC-1), and (iv) CD94/KLRD1 expressed on killer cells." (PMID 31533245, 2019). "Here, most HPV-positive tumors separated into clusters, mainly due to differences in the expression of immune related proteins on the cell surface of tumor infiltrating immune cells, e.g., PD-1, FasL, NCR1, and KLRD1 or soluble cytokines/chemokines e.g., IL12 and CCL4." (PMID 29587383, 2018). "Tumor-specific IL-7Rhi CD8+ T cells (cluster 4) expressed intrinsic cytotoxic mediators including natural killer cell granule protein 7 (Nkg7), killer cell lectin receptor D1 (Klrd1), cathepsin W (Ctsw), cystatin F (Cst7), and Ccl5, suggesting a capacity for cytotoxicity." (PMID 37459511, 2023). "To further assess the impact of CD56 on NK cell identification in lung tumors, we sorted tumor infiltrated cells into CD45- (not leukocyte cells) and CD45+ CD3- and with flow cytometry we analyzed the canonical CD16/CD56 combination, the CD122/CD94 (KLRD1/IL2RB) new marker pair or solely CD56." (PMID 41413116, 2025). "We found that the correlation of expression for CLIC6 and RAB30 in neighboring cells is higher in the ER+/PR+ group, while the correlation of expression for KLRD1 and LTB is higher in the ER‐/PR‐ group, regardless of whether the tumor is detected in the early or late stage." (PMID 40420636, 2026).
cancer (57 papers, 2007 to 2025). A tumor composed of atypical neoplastic, often pleomorphic cells that invade other tissues. "We systematically analyzed the expression characteristics of KLRD1 across various cancer types and its associations with genomic instability, immune microenvironment, and clinical prognosis." (PMID 39781341, 2025). "Analysis based on the cancer immunity cycle shows that KLRD1 is positively associated with immune cell trafficking but negatively correlated with other steps, such as immune cell priming, activation, and cancer cell killing." (PMID 39781341, 2025). "Research into KLRD1 is essential for developing novel cancer therapies by improving immune system detection." (PMID 39781341, 2025). "This consistent overexpression in NK cells highlights the role of KLRD1 as a marker for immune activity and a potential target in cancer immunotherapy." (PMID 39781341, 2025). "The results indicate that KLRD1 exhibits significant differential expression in multiple cancer types, with particularly strong relevance in HNSC, where its high expression correlates with better prognosis." (PMID 39781341, 2025). "Spearman correlation analysis revealed that in HNSC, KLRD1 is positively correlated with immune cell trafficking (Step 4) but predominantly negatively correlated with other steps of the cancer immunity cycle." (PMID 39781341, 2025). "Drug sensitivity was predicted using tools like CellMiner and the Genomics of Drug Sensitivity in Cancer (GDSC) database to explore the link between KLRD1 expression and responsiveness to various anticancer drugs." (PMID 39781341, 2025). "Although KLRD1-targeted immunotherapy is still in a developmental stage, researchers are actively exploring its potential applications across different cancer types and addressing possible resistance issues." (PMID 39781341, 2025). "Cancer cells recruited the CD4_T_cells_c2_CXCL13, CD8_T_cells_c1_GZMK, CD8_T_cells_c4_IFIT3, NK_cells_KLRD1, and Treg_cells_FOXP3 clusters through the CXCL10‐CXCR3 ligand–receptor pair." (PMID 36529697, 2023). "CD8+ cytotoxic T cells had elevated expression of the cytotoxic markers PD-1, Gzmb, Gzmk, Prf1, Nkg7, Eomes, Irf8, Klrd1, Fyn, Nfatc1, Tnfrsf9, and Zap70, supporting their killing function against cancer cells." (PMID 37762216, 2023). "Furthermore, KLRD1/NKG2A expression has been linked to autoimmune illnesses, infectious diseases, and a variety of cancers 11-15." (PMID 39781341, 2025). "Thses insight broadens our understanding of the impact KLRD1 has on cancer biology." (PMID 39781341, 2025). "We additionally identified as positive biomarkers several interactions between MHC-I genes and the corresponding receptors (HLA-B_HLA-E → KLRD1 and HLA-E → KLRC1 in 17 and 14 cancer types, respectively)." (PMID 34430923, 2021).
infection (40 papers, 2012 to 2025). The state of being infected such as from the introduction of a foreign agent such as serum, vaccine, antigenic substance or organism. "KLRD1 was expressed at approximately the same level at 6 hours and 24 hours after infection in both groups." (PMID 39836471, 2025). "In an HRV challenge cohort, symptom severity correlated negatively with expression of KLRD1 in the nasal epithelium 8 h post-infection." (PMID 29898768, 2018). "KLRD1 expression further decreased in the blood within the first 48 h of infection in both the discovery and validation cohorts." (PMID 29898768, 2018). "In a validation cohort, KLRD1 expression in the blood prior to infection differentiated between symptomatic shedders and asymptomatic nonshedders with high accuracy (AUROC = 0.91, 95% CI 0.75–1.0)." (PMID 29898768, 2018). "In a HRV challenge study, KLRD1 expression in nasal scrapings 8 h after infection negatively correlated with symptom severity." (PMID 29898768, 2018). "KLRD1 expression 8 h post-infection in the nasal epithelium from a rhinovirus challenge study also negatively correlated with symptom severity." (PMID 29898768, 2018). "One possibility for the reduction in KLRD1 expression in the blood following infection is that KLRD1-expressing NK cells are trafficking to the site of infection." (PMID 29898768, 2018). "KLRD1 expression significantly increased in nasal epithelium during infection with HRV or RSV." (PMID 29898768, 2018). "Therefore, we hypothesized that KLRD1-expressing cells rapidly traffic to the site of infection." (PMID 29898768, 2018). "Nodes 4 and 5 contain immune-related genes, including KLRD1 and NCR1, which regulate natural killer cell activity and surveillance, and CCL28 and CXCR6, which are involved in chemokine signaling and immune cell recruitment to infection sites." (PMID 41114509, 2025). "Furthermore, several additional transcripts associated with innate effector cell function were upregulated throughout acute infection, compared to pre-infection, including NKG7, KLRD1, EOMES, CD160, SLAMF5, and IL12RB1." (PMID 31937782, 2020). "Increased expression of KLRD1 and KLRC3 in nasal epithelium samples and reduced frequency of NK cells in peripheral blood samples are consistent with our hypothesis that the NK cells are actively recruited to the site of infection." (PMID 29898768, 2018).
cardiovascular disease (2 papers, 2015 to 2025). "Additionally, pathways associated with the excretory system, endocrine and metabolic diseases, cardiovascular diseases, and signaling molecules and interactions were significantly enriched in the KLRD1 high-expression group." (PMID 39781341, 2025).
KLRD1 also shares sentences with these, for which no sentence is quoted: HCMV infection (23 papers); HIV-1 infection (8); acute myeloid leukemia (6); autoimmune disease (6); glioma (6); leukemia (6); Crohn disease (5); ovarian carcinoma (5); colorectal cancer (4); myeloma (4); adeno lung carcinomas (3); celiac disease (3); glioblastoma (3); graft versus host disease (3); hepatocellular carcinoma (3); lung carcinoma (3); lymphoma (3); prostate carcinoma (3); systemic lupus erythematosus (3); acute lymphoblastic leukemia (2); cervical carcinoma (2); chronic graft versus host disease (2); gastric cancer (2); head and neck squamous cell carcinoma (2); hepatitis C (2); keloid (2); liver cancer (2); liver fibrosis (2); lung squamous cell carcinoma (2); metastatic melanoma (2).
A further 61 diseases each share a sentence with KLRD1 in 2 papers or fewer.